ATG4A (autophagy related 4A cysteine peptidase)
Description:
Cysteine protease that plays a key role in autophagy by mediating both proteolytic activation and delipidation of ATG8 family proteins. The protease activity is required for proteolytic activation of ATG8 family proteins: cleaves the C-terminal amino acid of ATG8 proteins to reveal a C-terminal glycine. Exposure of the glycine at the C-terminus is essential for ATG8 proteins conjugation to phosphatidylethanolamine (PE) and insertion to membranes, which is necessary for autophagy. Preferred substrate is GABARAPL2 followed by MAP1LC3A and GABARAP. Protease activity is also required to counteract formation of high-molecular weight conjugates of ATG8 proteins (ATG8ylation): acts as a deubiquitinating-like enzyme that removes ATG8 conjugated to other proteins, such as ATG3. In addition to the protease activity, also mediates delipidation of ATG8 family proteins. Catalyzes delipidation of PE-conjugated forms of ATG8 proteins during macroautophagy. Compared to ATG4B, the major protein for proteolytic activation of ATG8 proteins, shows weaker ability to cleave the C-terminal amino acid of ATG8 proteins, while it displays stronger delipidation activity. Involved in phagophore growth during mitophagy independently of its protease activity and of ATG8 proteins: acts by regulating ATG9A trafficking to mitochondria and promoting phagophore-endoplasmic reticulum contacts during the lipid transfer phase of mitophagy.
Synonyms: HsAPG4A; APG4A; AUTL2
Tractability: Small molecule: it has a high-quality binding pocket. PROTAC: ubiquitination databases record sites on it; a small molecule that binds it is known.
Target class: Enzyme; Hydrolase
Gene: Protein-coding gene on chromosome X (108,091,668 to 108,154,671, forward strand). Ensembl gene ENSG00000101844.
Subcellular location: Cytoplasm
Subcellular location (Human Protein Atlas): Microtubules; Actin filaments
Pathways (Reactome):
Autophagy: Macroautophagy
Gene Ontology:
Molecular function: cysteine-type peptidase activity; protein binding; protein-phosphatidylethanolamide deconjugating activity; cysteine-type endopeptidase activity
Biological process: autophagosome assembly; autophagy; protein delipidation; proteolysis; aggrephagy; mitophagy; piecemeal microautophagy of the nucleus; protein processing
Cellular component: cytoplasm
Homologues: Orthologues: chimpanzee ATG4A (99% identical), macaque ATG4A (98% identical), rabbit ATG4A (96% identical), guinea pig ATG4A (94% identical), dog ATG4A (94% identical), pig ATG4A (92% identical), rat AABR07040864.1 (92% identical), mouse Atg4a (92% identical), mouse Atg4a-ps (91% identical), tropical clawed frog atg4a (73% identical), zebrafish atg4a (69% identical), Caenorhabditis elegans atg-4.1 (42% identical), and 1 more. Paralogues in human: ATG4B (53% identical), ATG4D (30% identical), ATG4C (28% identical).
Diseases named in the same sentence as ATG4A in open-access papers:
ATG4A is named in the same sentence as 29 diseases in open-access papers, as found by Europe PMC text mining. Sharing a sentence is not in itself a finding about the gene and the disease. The quoted sentences say what the papers report.
breast carcinoma (6 papers, 2013 to 2025). "Knockdown of ATG4A with shRNA potentiated 4‐hydroxytamoxifen‐induced apoptosis in breast cancer cells." (PMID 40883962, 2025). "By conducting a mammosphere formation RNAi screening, it was revealed that ATG4A was essential to maintain a sub-population of cancer stem cells, and to regulate the tumorigenic potential of breast cancer cells in vivo." (PMID 35884904, 2022). "Further, the impact of ATG4A expression on sphere formation of breast cancer cell lines from different sub-types, namely basal MDA-MB-231 (CD44+/CD24-) and luminal MCF-7 cells (CD44-/CD24+) was analysed." (PMID 24229464, 2013). "ATG4A regulates mammosphere formation in several breast cancer cell lines as well as the maintenance of a sub-population with CSC properties." (PMID 24229464, 2013). "Furthermore, ATG4A levels influenced size and numbers of mammospheres formed from breast cancer cell lines of the luminal and, even stronger, the basal type." (PMID 24229464, 2013). "Furthermore, the autophagy regulator ATG4A was found to be essential for the maintenance of a sub-population with cancer stem cell properties and to regulate breast cancer cell tumourigenicity in vivo." (PMID 24229464, 2013). "In addition, the autophagy protein ATG4A was identified as a mediator of breast cancer." (PMID 35884904, 2022). "ATG4A and ATG4C are required for the survival of breast cancer stem cells or mammospheres formation, showing their important roles in the progress of breast cancer." (PMID 36980240, 2023). "Overexpression of ATG4A, but not ATG4B, in mammospheres reportedly contributes to breast cancer stem cell maintenance, owing to its importance in autophagosomal maturation." (PMID 25426560, 2015).
ovarian carcinoma (4 papers, 2019 to 2021). A malignant neoplasm originating from the surface ovarian epithelium. "ATG4A is associated with the clinical stage and progression-free survival in patients with ovarian cancer." (PMID 34636718, 2021). "Another report showed that hypomethylation of ATG4A predicted a poor prognosis for ovarian cancer patients." (PMID 34335109, 2021). "In another study, a high degree of methylation of ATG4A was observed in ovarian cancer patients, implying that ATG4A may have clinical significance in ovarian cancer." (PMID 31083460, 2019). "It is reported that ATG4A may be a biomarker of the prediction and prognosis of ovarian cancer." (PMID 34604383, 2021).
gastric cancer (3 papers, 2021 to 2025). A primary or metastatic malignant neoplasm involving the stomach. "Additionally, ATG4A overexpression significantly enhanced gastric cancer cell migration and invasion in vitro and promoted metastasis in vivo, likely through the activation of Notch signaling pathways." (PMID 40883962, 2025). "Furthermore, ATG4A overexpression induces the expression of the CSCs key genes, Sox-2, Oct-4 and Bmi-1, in gastric cancer cells." (PMID 33573362, 2021). "Overexpression of ATG4A has been shown to promote the epithelial‐mesenchymal transition (EMT) phenotype and stem‐like properties in gastric cancer cells, characterized by reduced E‐cadherin levels and elevated Sox‐2 expression." (PMID 40883962, 2025). "Consistent with this, ATG4A promotes the metastasis of gastric cancer cells in vivo and EMT in osteosarcoma via the Notch signaling pathway." (PMID 33573362, 2021). "Moreover, ATG4A is more highly expressed in gastric cancer tissues than in normal tissues and it can promote the EMT of gastric cancer cells." (PMID 34636718, 2021).
glioma (3 papers, 2019 to 2025). A benign or malignant brain and spinal cord tumor that arises from glial cells (astrocytes, oligodendrocytes, ependymal cells). "Then, CGGA dataset analysis showed that ATG4A expression was positively correlated to advanced stage of gliomas." (PMID 35341001, 2022). "Our findings capitulated that DLGAP1-AS1 targeted ATG4A to motivate glioma occurrence and development." (PMID 35341001, 2022). "In this study, we observed that ATG4A was upregulated in gliomas and correlated to shorter OS time in glioma." (PMID 35341001, 2022). "Our results showed that targeting DLGAP1-AS1/ATG4A may prove a potential biomarker for glioma treatment." (PMID 35341001, 2022). "Our conclusion suggested that DLGAP1-AS1 may be a potential prognosis biomarker and facilitated the occurrence and development of glioma via ATG4A in GBM." (PMID 35341001, 2022). "lncRNA DLGAP1-AS1 and ATG4A were overexpressed in the tissues and cells of glioma." (PMID 35341001, 2022). "Our data showed that DLGAP1-AS1 accelerated glioma cell migration and invasion via ATG4A." (PMID 35341001, 2022). "Although the roles of ATG4C and ATG4D in autophagy are less well‐characterized compared to ATG4A and ATG4B, knockdown of ATG4C has been shown to induce cell cycle arrest at the G1 phase and ROS‐mediated apoptosis in glioma cells, likely through suppression of autophagy." (PMID 40883962, 2025).
lung carcinoma (3 papers, 2017 to 2024). "ATG4A promoted the transition from epithelium to mesenchyme partly by the Notch signaling pathway in osteosarcoma cells and was related to reduced risk for lung cancer." (PMID 34335109, 2021).
osteosarcoma (3 papers, 2021 to 2025). A usually aggressive malignant bone-forming mesenchymal neoplasm, predominantly affecting adolescents and young adults. "For example, upregulating ATG4A would promote the transition of osteosarcoma cell epithelial to mesenchymal via the Notch signaling pathway." (PMID 35341001, 2022). "This study suggested that silencing ATG4 family members (ATG4A, ATG4B, ATG4C, and ATG4D) led to an increased proportion of cells in the G1 phase in osteosarcoma cells." (PMID 40883962, 2025).
viral infection (2 papers, 2022 to 2024). "In the current study, we sought to clarify the interaction between EV and ATG4A and determine the role of ATG4A during viral infection using CVB3 as a model enterovirus." (PMID 36146840, 2022). "The effectiveness of virus infection was evaluated by qPCR and IHC detection of ATG4a." (PMID 39572532, 2024). "Cell lysates were collected and probed with anti- Flag antibody to detect exogenous Flag-labelled ATG4A as well as anti-VP1 and anti-ACTB as viral infection and loading controls, respectively." (PMID 36146840, 2022).
chronic myeloid leukemia (1 paper, 2025). "Both ATG4A and ATG4B are upregulated in CD34+ chronic myeloid leukemia (CML) patients." (PMID 40883962, 2025).
colon cancer (1 paper, 2016). "However, BIX01294 induced changes could be cell-type specific, as in human colon cancer HCT116 cells the expression of LC3B, ATG9A, ATG4A, but not ATG4B/C, ATG7, BECN1, WIPI1 was increased after BIX01294 treatment." (PMID 27934912, 2016).
colorectal cancer (1 paper, 2022). A primary or metastatic malignant neoplasm that affects the colon or rectum. "Consistently, NEAT1 also induces autophagy by targeting miR-34a and miR-204 as a competing endogenous RNA (ceRNA) in colorectal cancer and HCC, respectively, resulting in the upregulation of autophagy-related proteins ATG9A, ATG4A, and ATG3." (PMID 36430876, 2022).
Diabetes (1 paper, 2021). "Although we did not detect any significant enrichment of specific biological processes by Gene Ontology (GO) analysis, we noticed that expression of autophagy-related genes (e.g., Bchs, Diabetes and obesity regulated (DOR), Stat92E, Atg4a, and Atg8a) were affected by rapamycin treatment." (PMID 33988501, 2021).
Hypertension (1 paper, 2023). The presence of chronic increased pressure in the systemic arterial system. "We have also shown that hypertension decreases autophagy-related 4A cysteine peptidase (Atg4a) in the rat cortex." (PMID 36707861, 2023).
keratinizing squamous cell carcinoma (1 paper, 2025). Squamous cell carcinomas with morphologically prominent production of keratin. "Positive expression of ATG4A was more prevalent in non-keratinizing squamous cell carcinoma (NKSCC) compared to keratinizing squamous cell carcinoma (KSCC) in the overall cohort of NPC patients (P = 0.005)." (PMID 40630202, 2025).
lymph node metastasis (1 paper, 2021). "By analyzing the expression of ATG genes both in TCGA and GSE62254, the results showed that VMP1 and ATG4A were over-expressed in patients with lymph node metastasis." (PMID 33604190, 2021). "Low expression of VMP1 and ATG4A suggested absence of lymph node metastasis (P = 0.0018, 0.015, correspondingly)." (PMID 33604190, 2021). "VMP1 and ATG4A were low-expressed in patients without lymph node metastasis." (PMID 33604190, 2021).
ovarian tumor (1 paper, 2025). "High expression of ATG4A is observed in ovarian tumor‐initiating cells, suggesting hypomethylation of ATG4A elevates ATG4A expression and promotes the stem properties and malignant phenotype of the cells." (PMID 40883962, 2025).
cancer (11 papers, 2013 to 2026). A tumor composed of atypical neoplastic, often pleomorphic cells that invade other tissues. "In human cancers, hypomethylation of the ATG4A gene is associated with poor prognosis in ovarian cancer." (PMID 40883962, 2025). "The ATG4 family (ATG4A, ATG4B, ATG4C, and ATG4D) encodes proteases essential for autophagy, a process implicated in cancer progression and drug resistance." (PMID 40883962, 2025). "Deletion of autophagy-related proteins, such as ATG4A, LC3B, and ATG12, has been associated with reduced cancer cell populations and decreased expression of vimentin, a promising marker of cancer progression." (PMID 39456967, 2024). "For example, in cancer samples, ATG4A cannot be fitted with any distribution, and the variance of its expression profiles is 87.70." (PMID 39541191, 2024). "Decreasing the level of autophagy-related proteins such as ATG4A decreases autophagy in cancer cells, resulting in tumor aggressiveness." (PMID 37506087, 2023). "In summary, we present a high-throughput screening system to identify genes involved in cancer stem cell maintenance and demonstrate its utility by means of ATG4A." (PMID 24229464, 2013). "The emerging role of autophagy in cancer stem cell maintenance together with the activation of lysosomal gene expression and upregulation of ATG4A in mammospheres strongly suggest an important role for autophagy, or more precisely, ATG4A in breast CSC maintenance." (PMID 24229464, 2013). "Tioconazole (TCZ), an antifungal drug, is able to occupy the active sites of autophagy-related proteases autophagy related 4A (ATG4A) or autophagy related 4B (ATG4B), and directly block their enzymatic activity 58, thus diminishing autophagic flux in cancer cells under stress conditions." (PMID 41510169, 2026). "ATG4 (ATG4A, ATG4B, ATG4C and ATG4D), a cysteine protease family, plays a crucial role in autophagy signaling and correlated with cancer progression in different types of cancers." (PMID 37038218, 2023). "Abnormal expression levels of some human VPS34, ATG4A and ATG16L1 genes occurs in several types of cancer cells, which may be closely related to tumor progression, tumor suppression and cancer therapy resistance." (PMID 30460069, 2017).
tumor (10 papers, 2013 to 2025). "ATG4A overexpression significantly accelerated tumour formation (P <0.01) whereas knockdown caused a reduced tumour burden (P <0.05) when compared to control cells." (PMID 24229464, 2013). "Previous researches revealed that ATG4A probably had a relationship with the stem-like phenotype, drug resistance, and neoplasm metastasis." (PMID 35341001, 2022). "ATG4A has been reported to promote tumor metastasis by inducing epithelial-mesenchymal transition and stem cell-like properties of gastric cells." (PMID 31967976, 2020). "Analysis of H&E-stained tissue sections revealed limited and circumscribed necrosis in control tumours, whereas ATG4A overexpressing tumours displayed extensive and diffuse necrotic areas." (PMID 24229464, 2013). "Moreover, the necrotic areas in ATG4A-overexpressing tumours displayed strongly elevated levels of inflammation as judged by the staining of neutrophil granulocytes (insert)." (PMID 24229464, 2013). "Last, modulation of ATG4A expression affected the tumourigenicity of SUM-149 cells under physiological conditions in the mammary fat pad of NSG mice as well as the composition of resulting tumours." (PMID 24229464, 2013). "Furthermore, at 15 weeks post injection, 100% of animals from the control group, but only 50% from the ATG4A knockdown group, had developed a tumour." (PMID 24229464, 2013). "In addition to autophagy, some reports have shown the function of ATG4A in tumor initiation." (PMID 35341001, 2022). "Taken together, ATG4A overexpression leads to an increased tumourigenicity of SUM-149 cells in NSG mice and to the development of tumours with a highly aggressive phenotype." (PMID 24229464, 2013). "The development of specific inhibitors of ATG4A and ATG4C may lead to new approaches for tumor treatment in the future." (PMID 34636718, 2021). "A large body of evidence suggests that inhibition of the activity of other ATG4 family members, including ATG4A, ATG4B and ATG4D, could suppress tumor progression and enhance chemosensitivity or the efficacy of radiotherapy." (PMID 31291988, 2019).
infection (6 papers, 2009 to 2023). The state of being infected such as from the introduction of a foreign agent such as serum, vaccine, antigenic substance or organism. "Furthermore, we tested the gene expression levels of ATG4A in sham and CVB3-infected cells and confirmed that gene expression was unaltered between sham and CVB3 at a timepoint of infection (7 h pi) when ATG4A protein was declining." (PMID 36146840, 2022). "One possibility is that the timing of cleavage could play a role given that ATG4A processing began 5 h post infection, a time point that is considered to be late stage of the viral lifecycle in HeLa cells." (PMID 36146840, 2022). "Taken together, these divergent observations suggest that ATG4A may have pro-viral functions during the early stages but anti-viral effects during late infection, providing a plausible explanation of viral-mediated cleavage of ATG4A during late infection." (PMID 36146840, 2022). "Beclin1/ATG6, ATG4A, 5, 12, and ATG16L2 have previously shown to be differentially expressed during infection with the intracellular pathogen Francisella tularensis." (PMID 27302320, 2016). "This notion is supported by evidence showing that intracellular infection with Francisella down-regulates several autophagy-related genes in THP-1 human monocytes, including ATG5, ATG12, ATG16L2, ATG7, ATG4A and class III PI3K." (PMID 20003180, 2009). "At 6 h post-infection (hpi), the enriched pathways included proteasome, ribosome, and regulation of autophagy, with the core genes of the most significantly enriched pathway in autophagy regulation (FDR = 0.2325) including ATG12, PIK3C3, GABARAPL1, ATG4C, and ATG4A." (PMID 37515115, 2023). "The mRNA expression of other ATG genes in WT, such as the mRNA expression of ATG4a and ATG4b decreased and then rise; the mRNA expression of ATG5 and ATG12a decreased with the infection time of AvrRpt2 (data not shown); these are very interesting." (PMID 32708160, 2020).
cardiovascular diseases (1 paper, 2024). "Several lncRNA–mRNA regulatory axes are involved in the action mechanisms of MSC-Exos in cardiovascular diseases, such as KLF3-AS1/sirtuin 1 (SIRT1), MALAT1/autophagy-related 4a (ATG4a), urothelial cancer associated 1 (UCA1)-Bcl-2, and Mir9-3hg/Pum2." (PMID 38812041, 2024).
ATG4A also shares sentences with these, for which no sentence is quoted: small cell lung carcinoma (3 papers); breast tumors (1); colorectal tumors (1); disc degeneration (1); encephalitis (1); musculoskeletal disorders (1); nasopharyngeal carcinoma (1); neuroblastoma (1); Obesity (1); rheumatoid arthritis (1).